IL6 (interleukin 6)
Diseases named in the same sentence as IL6 in open-access papers (continued):
Sharing a sentence is not in itself a finding about the gene and the disease.
muscle atrophy (31 papers, 2013 to 2025). The loss of muscle tissue due to inactivity or disease. "Insertion of the IL-6 gene into transgenic mice has been shown to elevate circulating IL-6, which is associated with severe muscle atrophy by the age of 10 weeks." (PMID 27746742, 2016). "We presented several findings from a range of studies which may indicate that proinflammatory markers (e.g., TNF-α and IL-6) may be responsible for the activation of pathways associated with muscle atrophy in poststroke patients (e.g., UPS system)." (PMID 27647951, 2016). "For instance, IL-6 has been reported to induce skeletal muscle atrophy, while TNF-α released by macrophages promotes muscle pyroptosis." (PMID 40940715, 2025). "Muscle atrophy in sarcopenic patients has the potential to stimulate the synthesis of myokines, such as interleukin-6 (IL-6) and IL-7, which can have a significant impact on the immune response." (PMID 40004687, 2025). "Muscle atrophy is often accompanied by elevations in inflammatory cytokines such as interleukin-6 (IL-6) and tumor necrosis factor-alpha (TNF-α), which induce alterations in the body’s consumption of proteins, lipids, and carbohydrates." (PMID 37589754, 2023). "Clinical literature also suggested that IL-6 is almost the only cytokine that increases among various factors in many patients with CAC muscle atrophy who lose weight." (PMID 34863141, 2021). "Among them, the JAK/STAT pathway has been confirmed to interact with IL-6 in a variety of muscle atrophy models." (PMID 34552592, 2021). "As with other muscle atrophy mice models, IL-6 was increased by the injection of CT-26 cells and muscle atrophy was also reproduced." (PMID 33086629, 2020). "Muscle atrophy is strongly linked to an increase in the generation of inflammation-inducing cytokines, including TNF-α (tumor necrosis factor-alpha), IL-1 (interleukin-1), IL-6 (interleukin-6), and IFN-γ (interferon-gamma)." (PMID 38732255, 2024). "Moreover, the contribution of the Piezo1/KLF15/IL-6 axis to immobilization-induced muscle atrophy identified in mice was validated with the use of biopsy samples of patients with cast fixation–induced skeletal muscle atrophy." (PMID 35290243, 2022). "Previous studies have shown that IL-6 is one of the predictors of CAC-induced muscle atrophy, which may aggravate the disease development." (PMID 34863141, 2021). "These factors and downstream molecules of IL-6 may become new targets for the therapy of muscle atrophy." (PMID 34552592, 2021). "Muscle atrophy as a result of chronic inflammation is associated with increased proinflammatory cytokine production, such as tumour necrosis factor alpha (TNF-α), interleukin 1 (IL-1), interleukin 6 (IL-6), and interferon gamma (IFN-γ; 59)." (PMID 28690764, 2017). "Muscle atrophy is sometimes observed in MG patients, especially in type II fibers, but whether atrophy is due to the increased IL-6 production by the autoantibodies remains an open question." (PMID 25627031, 2015). "Therefore, we hypothesized that the inhibition of systemic IL-6 in a disuse-induced muscle atrophy model might be a strategy to repress atrogene expression and to counteract the atrophy." (PMID 29351340, 2018). "Furthermore, few studies have examined whether vitamin D and HMB ameliorate disuse-induced muscle atrophy, or whether the effect is via IL-6-related pathways." (PMID 29351340, 2018). "Muscle atrophy was observed in CM-treated myotubes due to the increase in inflammatory cytokines including TNF-α, interleukin-6, interleukin-1β and interferon-γ." (PMID 29258243, 2017). "Further investigation of IL-6–dependent amino acid metabolism in BAT and skeletal muscle may inform the development of preventive or therapeutic interventions for some forms of muscle atrophy." (PMID 41143503, 2025).
muscle atrophy (continued). "We also discovered that inflammation-related genes (TNF-, IL-6, and IL-1b) showed no changes even after 5 weeks of EVs-Cas9-29b therapy in IMO- and Den-induced muscle atrophy which is coincidentally the endpoint of the treatments." (PMID 35761332, 2022).
Myalgia (31 papers, 2012 to 2026). "The accumulated IPP in monocytes and macrophages activates and proliferates γδ T cells, causing the release of pro-inflammatory cytokines TNFα and IL6, which can lead to an acute systemic inflammatory response, manifested as headaches, myalgia, flu-like symptoms." (PMID 39640483, 2024). "Additionally, another phenomenon associated with myalgias is the “cytokine storm”, in which interleukin-6 plays a key role in inducing the production of prostaglandin E2, associated with inflammation and pain." (PMID 36233459, 2022). "Colocalization analysis also revealed significant evidence of a shared causal variant between polymyalgia rheumatica and CRP levels in the IL6 locus (PP.H4 = 0.85)." (PMID 40858837, 2025). "The one subject who reported moderate myalgias and injection site pain after vaccination displayed a distinctive, early cytokine response profile which included IL‐6, IL‐2, IL‐8, IP‐10, MCP‐1, TNF‐α, TARC, and MCP‐4." (PMID 28991404, 2018). "Some positive clinical correlations (weak to moderate) of interest need to be mentioned- IFN-γ and pain intensity, IFN-β, IL-1β individually and fatigue, TNF-α and headache, IL-4 and myalgia, IL-6 and skin rash." (PMID 25343623, 2014). "The role of involvement of IL-6 and other cytokines in different aspects of chronic myalgia needs further investigation." (PMID 25348119, 2014). "Finally, using this approach, we detected anassociation between the IL6 receptor signal transduction gene IL6ST and polymyalgia rheumatica, an indication for which sarilumab, a monoclonal antibody against IL-6, has been recently approved." (PMID 39563277, 2024). "Elevated levels of the pro-inflammatory factor interleukin-6 may be responsible for the myalgia and joint pain." (PMID 34539642, 2021). "Subjects experiencing myalgia had higher levels of IP‐10 and IL‐6 at 7 hours after vaccination." (PMID 28991404, 2018). "Thus, the IL-6 pathway represents the intersection of the innate and acquired immune systems and, when unregulated, maintains inflammation both in polymyalgia rheumatica and in GCA." (PMID 24963300, 2014). "The first study reported elevated masseter muscle levels of IL-6, IL-7, IL-8, and IL-13 in patients with TMD myalgia compared to a control group." (PMID 40142185, 2025). "Microdialysis revealed that the levels of IL-6, IL-7, IL-8 and IL-13 were higher in patients with TMD-related myalgia than controls." (PMID 37509035, 2023). "This study showed that the muscle levels of IL-6, IL-7, IL-8 and IL-13 were increased in patients with TMD myalgia and increased further in response to experimental tooth-clenching, as did jaw-muscle pain and fatigue." (PMID 28243900, 2017). "In conclusion, the masseter levels of IL-6, IL-7, IL-8 and IL-13 were elevated in patients with TMD myalgia and increased in response to tooth-clenching." (PMID 28243900, 2017). "Tooth-clenching increased IL-6, IL-7, IL-8, TNF and IL-13 in TMD myalgia patients and IL-6 and IL-8 in controls, in line with previous studies." (PMID 28243900, 2017). "IL-6, CXCL-10/IP-10, CRP and presence of knee pain and myalgia were found to significantly predict persistence of post CHIKV musculoskeletal pain." (PMID 25343623, 2014). "Interleukin 6 (IL-6) and interleukin 8 (IL-8) levels increased in response to tooth clenching in both groups, while interleukin 7 (IL-7), interleukin 13 (IL-13) and tumor necrosis factor (TNF) rose only in patients with TMD-related myalgia." (PMID 37509035, 2023). "Those reporting myalgia at follow‐up had a significantly lower median IL‐6 level compared with those not reporting this symptom (34.9 vs. 49.5 pg/mL), p = .043)." (PMID 37904690, 2023). "The main findings were that the masseter levels of IL-6, IL-7, IL-8 and IL-13 were higher in TMD myalgia patients than controls and that repetitive tooth-clenching increased the levels of IL-6 and IL-8 in both groups, while IL-7, IL-13 and TNF increased only in patients." (PMID 28243900, 2017).
Myalgia (continued). "In this study, we evaluated the activity of the neuroendocrine axes in patients with polymyalgia rheumatica (PMR) before and after tumor necrosis factor (TNF)-α-blocking etanercept treatment, which previously has been shown to reduce interleukin 6 (IL-6) and C-reactive protein (CRP) markedly in PMR." (PMID 22894827, 2012). "This is the first study to show elevated muscle levels of the pro-inflammatory cytokines IL-6 and IL-8 and the anti-inflammatory cytokines IL-7 and IL-13 in painful jaw muscles of patients with TMD myalgia which supports the hypothesis that patients with TMD myalgia have higher levels of cytokines." (PMID 28243900, 2017).
neuropathic pain (31 papers, 2009 to 2025). Chronic pain caused by damage to nerve fibers. "Furthermore, the findings suggested that IL-1β and IL-6 are responsible for the emotional dysfunction associated with neuropathic pain." (PMID 33432004, 2021). "Several pro-inflammatory cytokines, including IL-1β, IL-6, IL-18, and TNF-α, have been implicated in the development of neuropathic pain." (PMID 35770074, 2022). "During pathogenesis of neuropathic pain, activated microglia produce and release a variety of pro-inflammatory cytokines (e.g., IL-1β, TNFα, IL-6, and CCL2) and BDNF to sensitize spinal neurons." (PMID 33739978, 2021). "It was previously reported that administration of IL-6 neutralizing antibodies diminishes pain behavior in neuropathic pain models." (PMID 32691345, 2020). "It is known that IL-1β, IFN-γ, IL-17, IL-6 and TNFα are increased in nervous tissue in animal models of neuropathic pain, but also in cerebrospinal fluid and blood of patients with neuropathic pain." (PMID 32708184, 2020). "Pro-inflammatory cytokines such as IL-1β, IL-6, and TNF-α have been associated with the behaviors of hyperalgesia and mechanical allodynia in the CCI model of neuropathic pain." (PMID 24605047, 2014). "Several studies have shown that the mRNA and protein levels of the pro-inflammatory cytokines TNF-α, IL-1β and IL-6 increased following chronic morphine injection and neuropathic pain." (PMID 24573601, 2014). "Spinal administration of IL-6 has anti-nociceptive effects in the spinal nerve ligation neuropathic pain model measured by a dose-related inhibition of electrically evoked C-fibre activity." (PMID 20003309, 2009). "Moreover, findings from neuropathic pain models—such as improvements in nerve conduction and reductions in pro-inflammatory cytokines (e.g., IL-6, TNF-α, CRP)—lend additional biological plausibility, although the certainty of this evidence remains limited." (PMID 41441449, 2025). "The data further support that gp130 signaling contributes to inflammation-evoked mechanical hyperalgesia, corresponding to the sensitization of nociceptive sensory neurons for mechanical stimuli by IL-6 that has been previously reported for the complete Freund’s adjuvant and neuropathic pain models." (PMID 26590032, 2015). "Similarly, IL-1β and IL-6 are related to the pathogenesis of neuropathic pain." (PMID 37081929, 2023). "EE can relieve neuropathic pain by reducing inflammatory mediators, such as proinflammatory cytokines (IL-1β, TNF-α, IL-6) and chemokines (CCL2, CCL3), among others, increasing anti-inflammatory substances (IL-10, Arg-1, CX3CL1) in the periphery and CNS." (PMID 40190342, 2025). "In our study, PTP1B‐IN‐1 administration effectively suppressed the elevated Iba‐1, GFAP, TNF‐α, IL‐6, and IL‐1β in SNI‐induced neuropathic pain rats." (PMID 38334011, 2024). "Similarly, high IL-6, IL-17A, and TNFα levels were observed in the serum of lumbar radiculopathy patient group compared with the neuropathic pain group, and Th17 was higher in the venous blood of lumbar radiculopathy patients group compared with the neuropathic pain group." (PMID 35309927, 2022). "In the case of hesperidin, its antihyperalgesic effects in neuropathic pain have been related to the presence of cytokines concentrations (TNF-α, IL-1β and IL-6) in both peripheral and central tissues." (PMID 34371971, 2021). "Studies have shown that NF-κB is observed to regulate the expression of pro-inflammatory cytokines such as TNF-α, IL-1β and IL-6 in DRG and spinal cord in neuropathic pain." (PMID 33095154, 2020). "Minocycline has also indicated to reduce the cytokine levels (IL-1β, TNF-α, and IL-6), which promoted neuro-inflammation and decreased pain behavior in a CCI model of neuropathic pain." (PMID 27221523, 2016). "For example, spinal LXA4 and its aspirin-triggered form reduced TNF, IL-1β and IL-6 mRNA and protein levels in the DRG in a neuropathic pain model and in the spinal cord in a model of bone cancer-induced pain." (PMID 24086560, 2013).
neuropathic pain (continued). "Interestingly, it has been determined that the upregulation of IL-6, IL-1β, and TNF-α, among others, strongly influences neuropathic pain." (PMID 39684195, 2024). "Microglial MAP kinases can be activated by IL-1β and TNF-α, inducing, via transcription factors such as NFκB, additional production of IL-1β, TNF-α, IL-6, IL-10, TGF-β, PGE2, BDNF, and cathepsin S and promoting the deleterious effects of microglial infiltration and phagocytosis in neuropathic pain." (PMID 24642655, 2014).
skin cancer (31 papers, 2010 to 2026). "The functional activity of IL-6 is dysregulated in a variety of malignancies, including breast, lung, pancreatic, colorectal, gastric, blood, and skin cancers, and high serum IL-6 levels are associated with bad prognosis in cancer patients." (PMID 31491838, 2019). "Mice deficient of TNF or IL6 are more resistant to DMBA/TPA-induced skin tumor formation." (PMID 28467300, 2017). "We previously demonstrated that MCPIP1 affects skin cancer progression by regulating the expression of inflammatory molecules such as IL-6, IL-33 and TGF-β." (PMID 39428471, 2024). "Thereafter, the possible suppression of induced IL-6 response was measured from the cultured skin cancer cell lines A2058 and A431, and normal primary keratinocytes with Enzyme-Linked Immunosorbent Assay (ELISA)." (PMID 37292297, 2023). "Taken together, these experiments demonstrate the significance of the cross-talk between stromal and tumour cells in cancers of the skin and elucidate the mechanisms by which IL-6 is able to promote invasiveness in cancers of the skin." (PMID 36429126, 2022). "The most aggressive form of skin cancer is melanoma which is characterized by upregulation of several pro-inflammatory cytokines, including IL-6, IL-8, CCL5, and IL-1β, the expression of which can be regulated by IL-1β5,64,66." (PMID 33686176, 2021). "Together with increased pro-inflammatory mediators such as IL-6 and IL-8, we conclude that plasma treatment spurs stress responses in skin cancer cells, eventually augmenting NK-cell activity." (PMID 33265951, 2020). "In skin carcinoma, IL-6-induced VEGF-A contributes to tumor growth in an autocrine loop." (PMID 40746859, 2025). "Interestingly, another study has shown that NIPP treatment promotes the induction of IL-6 and IL-8 in skin cancer cells." (PMID 39629237, 2024). "Our studies clearly show that E2F1-STAT3/IL-6 produced by skin cancer cells shifted the Th1/Th2 balance toward the Th2 phenotype, whereas depletion of E2F1 in turn caused a pronounced decrease in type-2 cytokines that potentially determines the development and responsiveness of Th1 cells." (PMID 39544930, 2024). "Therefore, we investigated if P. major was able to modulate LPS and IFN-γ induced IL-6 release from primary keratinocytes and skin cancer cell lines." (PMID 37292297, 2023). "In addition to IL-22, IL-6 and IL-11 also drives the malignant progression of skin cancer cells through the activation of STAT3 and upregulation of inflammatory and angiogenic factors." (PMID 31051015, 2016). "Infliximab could reduce skin inflammation in NS, decreasing the expression of TSLP, IL-6, and IL-8, but the treatment is not recommended considering the risk of skin cancers and recurrent infections reported in patients." (PMID 34041207, 2021). "It appears that skin cancer cells and benign oral cells also respond differently to NIPP therapy in terms of IL-6 and IL-8 secretion." (PMID 39629237, 2024). "Our results indicate that IL-6 produced by prenatally conditioned fibroblasts plays a major role in regulating the KSC niche and promoting skin tumor development in As-exposed offspring." (PMID 38519574, 2024). "Although curcumin has previously been shown to inhibit IL-6 in HNSCC cell lines, this is the first skin cancer model investigating curcumin's inhibition of systemic IL-6." (PMID 23316365, 2012). "It is a safe agent preventing UVB-induced skin cancer via targeting inflammatory mediators (lowering COX-2, PGE2, PCNA, TNF-α, IL-1β, and IL-6 levels), cell cycle regulators (CDK inhibitor upregulation), and cell survival signals (cyclins D1, D2, E2 and CDKs2, 4, 6 inhibition)." (PMID 40943669, 2025). "Although the role of AFs and IL-6 in skin cancer has not been extensively studied, our findings show that prenatally AFs release IL-6, which promotes the phosphorylation of JAK2 and STAT3 in KSCs." (PMID 38519574, 2024).
skin cancer (continued). "In supernatants of co-cultures of NK-cells with either of the skin cancer cell lines but not HaCaT keratinocytes, we identified elevated IL-6 and IL-8 levels in plasma conditions." (PMID 33265951, 2020). "Although the in vivo test on IL-6 in mouse models of skin cancer is lacking at this point, cell line-based studies have shown that IL-6 plausibly promotes skin tumor growth through activation of the STAT3 transcription factor." (PMID 31051015, 2016). "Further, although IL-6 signaling promotes skin tumor growth and angiogenesis in a paracrine fashion, we did not detect any difference between KrasG12D and KrasG12D; IL-6-/- mice after immunohistochemical staining with Endomucin, a microvessel density marker to measure angiogenesis index." (PMID 24260500, 2013).